ATF6 (activating transcription factor 6)
Diseases named in the same sentence as ATF6 in open-access papers (continued):
Sharing a sentence is not in itself a finding about the gene and the disease.
reovirus infection (1 paper, 2020). "After reporter validation, ATF4, IRE1, and ATF6 reporter levels were imaged after 72 h of reovirus infection and GSK2606414 treatment." (PMID 32128359, 2020).
sarcoma (1 paper, 2005). A usually aggressive malignant neoplasm of the soft tissue or bone. "Based on their consistent association with this amplicon and possible roles in promoting cell growth, both ATF6 and DUSP12 represent interesting candidate target genes for the 1q23 amplification in sarcomas." (PMID 16274472, 2005). "ATF6 and DUSP12 seem to be the most likely candidate target genes for the 1q23 amplification in sarcomas." (PMID 16274472, 2005).
SARS-CoV infection (1 paper, 2011). "No significant activation of ATF6 was observed in infected cells, compared to mock-infected cells (data not shown), suggesting that SARS-CoV infection did not efficiently activate this pathway." (PMID 22028656, 2011).
scrapie (1 paper, 2013). A fatal disease of the nervous system in sheep and goats, characterized by pruritus, debility, and locomotor incoordination. "Our results show that in the older (sick) TgMHu2ME199K mice brains as well as in scrapie infected brains, truncated ATF6 (representing activated ATF6) was significantly accumulated, concomitantly with the accumulation of PK resistant PrP." (PMID 23349890, 2013). "We now tested the levels of activated ATF6 (activating transcription factor), a major UPR protein responsible for the up regulation of chaperones such as BIP in the brains of TgMHu2ME199K, scrapie infected and wt mice." (PMID 23349890, 2013).
sensorineural hearing loss (1 paper, 2025). "Here, we report that hair cells in the OC also require ATF6 for function and viability and that loss of ATF6 leads to a second human disease — sensorineural hearing loss, which is phenocopied in Atf6–/– mice." (PMID 39570676, 2025).
serous ovarian cancer (1 paper, 2020). "Moreover, we found a significant correlation between the expression of ID1 and ATF6 in 1104 high grade serous ovarian cancer tissues, and that patients with the high expression of ID1 or ATF6 were resistant to platinum treatment and had the poor overall survival and progression-free survival." (PMID 32080166, 2020).
tendinopathy (1 paper, 2025). "RNA-seq analysis identified ATF6 as a significantly upregulated gene in patients with hypervascularized tendinopathy, and its expression was also found to increase progressively in the Td-Inj and Td-Sut groups, suggesting that ATF6 may contribute to sustained angiogenesis." (PMID 41258071, 2025).
Thrombocytopenia (1 paper, 2022). A reduction in the number of circulating thrombocytes. "Thus, abnormal regulation of ATF6 may interfere with the differentiation of normal megakaryocytes, eventually leading to thrombocytopenia." (PMID 36422902, 2022).
Usher syndrome (1 paper, 2025). A syndromic diseae characterized by the association of sensorineural deafness (usually congenital) with retinitis pigmentosa and progressive vision loss. "Many Usher syndrome proteins are structural components of stereocilia in hair cells and ciliary/periciliary/calyceal processes in photoreceptors, whereas ATF6 is an ER membrane–bound transcription factor that regulates ER protein-folding fidelity." (PMID 39570676, 2025). "Many mouse models of Usher syndrome recapitulate the auditory defects found in patients but show little to no vision defects, and Atf6–/– mice also exhibit hearing loss but retain normal vision until 18 months of age, when a gradual decline in photopic and scotopic responses occurs." (PMID 39570676, 2025). "At the subcellular level, Usher syndrome genes and ATF6 share no obvious mechanistic functions." (PMID 39570676, 2025).
Uterine leiomyoma (1 paper, 2025). The presence of a leiomyoma of the uterus. "Interestingly, MA exhibited an anti-proliferative effect on uterine leiomyoma cells by targeting SOAT, which impaired cholesterol esterification, leading to ER stress-induced cell death by provoking UPR sensors, PERK, IRE1, and ATF6." (PMID 39863145, 2025).
vascular ED (1 paper, 2024). "The endoplasmic reticulum (ER) stress, linked with vascular ED, includes the activation of the inositol requiring enzyme 1 (IRE1) and activating transcription factor 6 (ATF6) pathways, and the induction of activating transcription factor 4 (ATF4)." (PMID 38172976, 2024).
viral myocarditis (1 paper, 2024). Myocarditis that is caused by an infection with a viral agent. "To pinpoint which among these sensor-mediated signaling pathways intersects with TRIM29 expression during viral myocarditis, we assessed the expression levels of PERK, IRE1α and ATF6 in cardiomyocytes." (PMID 38664417, 2024).
tumor (155 papers, 2005 to 2026). "Taken together, our findings clearly indicate an early pre-tumour microbial adaptation to the ATF6-altered FA-rich intestinal environment, to shape a tumour-associated bacterial lipid-response signature." (PMID 40890536, 2025). "Of note is the observed overlap in specific tumour-associated and ATF6-associated taxa between mouse and human microbiota, namely D. fairfieldensis, Oscillibacter spp., Desulfovibrionaceae spp." (PMID 40890536, 2025). "We characterize ATF6 expression in multiple independent German CRC cohorts and causally link chronic ATF6 activity to altered lipid metabolism and tumour-relevant microbiota changes." (PMID 40890536, 2025). "In colorectal cancer, elevated ATF6 activity has been observed in tumor tissues, where it reprograms fatty acid synthesis in intestinal epithelial cells, underscoring its role in tumor-associated lipid metabolic remodeling." (PMID 41350297, 2025). "We provide evidence that the mechanism underlying tumor-growth defects conferred by ATF6 disruption involves attenuation of Wnt and Myc signaling, reduced cell-cycle progression and stemness, and increased differentiation." (PMID 39324706, 2024). "We propose that PTEN mutation or inactivation is one means by which tumor cells become resistant to ER stress-induced apoptosis, resulting in increased ATF6 and enhanced Entpd5/IGF1R expression, promoting protein glycosylation and folding." (PMID 36824269, 2023). "With respect to the causal role of the UPR effector ATF6 in tumor biology, very little is known, although its downstream target gene Grp78 is frequently found to be overexpressed." (PMID 31867005, 2019). "Likewise, ATF6 signaling has also been implicated in promoting resistance in glioblastoma and lymphoma, where its knockdown sensitizes tumor cells to radiotherapy or chemotherapy, respectively." (PMID 41228282, 2025). "Although less extensively characterized, ATF6 has been implicated in hypoxic tumor contexts and may also intersect with autophagy pathways to contribute to cellular adaptation." (PMID 41350297, 2025). "ATF6α functions as a transcription factor, which may be associated with the regulation of tumour cell dormancy." (PMID 38297380, 2024). "Additionally, ATF6 controls the expression of specific proteins associated with tumor transformation and increased chemoresistance." (PMID 37221596, 2023). "Targeting ATF6 in dormant tumor cells prolonged the survival of dormant tumor cell–bearing nude mice, suggesting that the ATF6 signal was involved in acquiring a dormant phenotype of tumor cells, which causes cancer recrudescence." (PMID 36408145, 2022). "In meningiomas, ATF6 expression levels were associated with tumor aggressiveness." (PMID 35784465, 2022). "Effector ATF6 is the causal role of the UPR in tumor biology." (PMID 33514437, 2021). "Mechanistically, IMMT loss promotes ATF6α-ATF6β heterodimer formation, whereby ATF6α stabilizes ATF6β protein, enabling ATF6β to engage PPARγ through direct physical interaction and orchestrate redox homeostasis remodeling that sustains tumor cell proliferation." (PMID 42049712, 2026). "ATF6α downregulation induces apoptosis in dormant tumor cells and markedly prolongs survival in mice bearing dormant disease." (PMID 41438587, 2026). "Our findings suggest that persistently activated ATF6α is a tumour driver, a potential stratification marker for ICB response and a therapeutic target for HCC." (PMID 41639449, 2026). "ATF6α activation in human HCC is significantly correlated with an aggressive tumour phenotype, characterized by reduced patient survival, enhanced tumour progression and local immunosuppression." (PMID 41639449, 2026). "ATF6 is a key regulator of tumor growth, malignant progression, and chemoresistance; additionally, it has an impact on autophagy and the microbiota." (PMID 40035165, 2025). "The PERK, IRE1α, and ATF6 signaling pathways play a crucial role in the immune regulation, invasion, and migration of tumor cells." (PMID 40978046, 2025).
tumor (continued). "Aberrant activation of the UPR sensors (IRE1α-XBP1, PERK-ATF4, ATF6) and their downstream signaling pathways have emerged as critical regulators of tumor angiogenesis, metastasis, and response to chemotherapy, targeted therapy, and immunotherapy." (PMID 40745648, 2025). "Tumor volumes were measured every four days, revealing that tumor growth in the sh-ATF6 group was significantly slower compared to the sh-ATF6 + OE-TRIM37 group." (PMID 40158112, 2025). "Immunofluorescence results showed that the expression levels of IRE1α and XBP1s in NSCLC tumor tissues were also significantly increased compared to that of the other two key genes, ATF6 and PERK, in the UPR pathway." (PMID 41254082, 2025). "We postulate chronic ATF6 signalling to select for tumour-promoting microbiota by altering lipid metabolism." (PMID 40890536, 2025). "IRE1α and ATF6 pathways have a very context-dependent role in tumor progression that depends on the extent of ER stress involved." (PMID 41301006, 2025). "It has also been demonstrated that ATF6 regulates the survival of dormant tumor cells in the human body." (PMID 40547943, 2025). "While ATF6 activation initially supports cell survival during early tumor development by alleviating ER stress, its sustained activation has been linked to tumor progression and metastasis." (PMID 40223122, 2025). "Genetic or pharmacological inhibition of ATF6α has been shown to interfere with tumor survival and is a potentially exploitable therapeutic target." (PMID 41154810, 2025). "Our data suggest a clear link between ATF6-induced lipid alterations and changes in the intestinal microbiota preceding tumour formation." (PMID 40890536, 2025). "To further explore the role of the ATF6α-ΔNp63α axis in tumor metastasis, we utilized a tail vein injection mouse metastasis model." (PMID 40223122, 2025). "Most importantly, we identified a mechanism through which ATF6-mediated changes in cellular lipid metabolism of the intestinal epithelium contribute to the development of tumour-promoting microbiota changes at an early disease stage." (PMID 40890536, 2025). "In dormant squamous cell carcinoma, the nuclear translocation of ATF6 enhances the ability of tumor cells to withstand stresses such as chemotherapy and nutrient deprivation." (PMID 41209558, 2025). "One possible weakness is the unfolded protein response (UPR), a cellular stress-response system mediated by three main proteins—IRE1, PERK, and ATF6—which help cells adapt but can also promote tumor growth, survival, and resistance to therapy." (PMID 41228282, 2025). "For instance, the activation of UPR signaling pathways, including IRE1, PERK, and ATF6, has been shown to support tumor growth and metastasis by promoting cell survival, angiogenesis, and immune evasion." (PMID 40547943, 2025). "CRC tissues exhibit elevated ATF6 expression, suggesting its involvement in tumor growth and ER adaptability." (PMID 39813534, 2025). "While the inhibition of ATF6α activation is an established mechanism through which Melatonin hinders tumorigenesis and tumor progression, it is important to note that Melatonin's antitumor effects have been substantiated in various studies." (PMID 40547943, 2025). "Previous tumor studies have shown that ATF6 is a key factor determining the trends of tumor cell proliferation, apoptosis, and invasion and metastasis in solid tumors." (PMID 40158112, 2025). "This complex cellular pathway, mainly regulated by sensors such as IRE1, PERK, and ATF6, performs distinct functions in modulating tumor survival and development, promoting or inhibiting tumor growth depending on the cancer type." (PMID 40278350, 2025). "and Bilophila spp., supporting a causal link between ATF6-mediated LCFA synthesis and tumour-relevant changes in the microbiota." (PMID 40890536, 2025). "Although ATF6α is proposed to promote the dormancy of tumour cells and resistance to chemotherapeutic drugs, ATF6α inhibitors have rarely been developed." (PMID 38297380, 2024).
tumor (continued). "Its three arms IRE1, PERK, and ATF6 activate their downstream pathways furthering tumor cell survival, proliferation and the development of chemoresistance." (PMID 39021040, 2024). "Analysis of these data revealed that tumor cells displayed increased ER13 expression as well as ATF6 expression, as compared with colonic normal cells." (PMID 39324706, 2024). "This study found that tumor protein D52 (TPD52) integrates ER stress by promoting S2P‐mediated cleavage of ATF6, thus inhibiting tumor progression." (PMID 39401430, 2024). "In this vein, CRISPR interreference of ATF6 in HCT116 cells required concomitant deletion of IRE1α to reduce tumor growth, which indicates that both UPR branches can play a role at least in some circumstances." (PMID 39324706, 2024). "ASP exerts its anti-tumor effects by down-regulating ATF6, thereby inhibiting the activation and function of pancreatic CAFs." (PMID 38896161, 2024). "The three branches of the UPR: PERK and IRE1 are activated in response to oncogenes and ATF6‐dependent pathways are activated to a lesser extent to promote the tumor initiation." (PMID 39021040, 2024). "Regardless, it is conceivable that the tumor promoting role of ATF6 extends beyond Wnt signaling, for example, in protecting against DNA damage." (PMID 39324706, 2024). "ATF6 is mainly manifested in the acquisition of tumor resistance or sensitization, where it can promote tumor resistance via P58, or act downstream of carfilzomib, achieving tumor resistance in patients resistant to cetuximab." (PMID 39080273, 2024). "It has been demonstrated that ATF6 sustains activation of the mammalian target of rapamycin (mTOR) pathway, a vital element in tumor metabolism." (PMID 39080273, 2024). "A more comprehensive examination of the interactions and influences of the UPR’s tripartite branches IRE1, PERK, and ATF6 on tumor biological behaviors, including growth, invasion, metastasis, and angiogenesis, is imperative." (PMID 39080273, 2024). "In contrast, there is a significant difference in PIGV levels between tumor and paratumor, suggesting that ATF6-miR449c-5p–decreased PIGV expression is tumor cell–dependent." (PMID 37390992, 2023). "In these tumors, silencing ATF6 reduces cell survival and tumor growth by downregulating adaptive pathways such as mTOR." (PMID 37221596, 2023). "High ATF6α expression enhances Pla2G4A‐mediated AA metabolism and protects tumor cells against iron downregulation to promote the progression of PCa." (PMID 37746665, 2023). "Deletion of ATF6 in polymorphonuclear MDSCs promoted Ag-specific responses and delayed tumor growth in animals." (PMID 37067519, 2023). "PPM1H-overexpressing cells co-infected with ATF6 displayed a little bit larger xenogeneic tumor size than cells co-infected with a control lentivirus; however, the results were statistically not significantly different." (PMID 37456776, 2023). "We have demonstrated that a decrease in the OCT-1 levels in tumor cells leads to a decrease in the transcription activity of the ATF6 response elements present in the regulatory region of the ATP6 target genes." (PMID 36143471, 2022). "Most UPR signaling pathways are initiated by IRE1α, PERK, and ATF6, making them critical for tumor growth and aggressiveness, microenvironmental remodeling, as well as treatment resistance." (PMID 36698399, 2022). "The differences in the prognostic values between ATF6 and ATF6B are also reflected by the different expression levels of these two ATF6 genes between normal lung tissue and tumor tissues." (PMID 35625704, 2022). "ATF6 is found constitutively active in quiescent tumor cells where it supports dormancy by regulating the mTOR pathway." (PMID 36139473, 2022). "The suppression of ATF6 or the Ras homolog enriched in brain (Rheb) reinstates rapamycin resistance in dormant tumor cells, revealing the regulation of autophagy in tumor cells via the ATF6-Rheb-mTOR pathway." (PMID 36497032, 2022).